TNF (tumor necrosis factor)
Diseases named in the same sentence as TNF in open-access papers (continued):
Sharing a sentence is not in itself a finding about the gene and the disease.
psoriasis (continued). "Though the side effect is a well-established phenomenon, its pathogenesis had remained elusive and only recently, the dysbalance of TNF and type-I IFN (yin-yang of TNF and IFNα) has been confirmed as a pathogenic mechanism underlying paradoxical psoriasis." (PMID 30555460, 2018). "In the current study, the variant allele of TNF (rs361525) was the only variant consistently associated with an increased risk of all phenotypes, thus underlining the importance of TNF-α signaling in the development of psoriasis." (PMID 29389950, 2018). "Our results are also corroborated by the research report of Young’s group, which has documented that ROS are involved in TNF-α-mediated signaling pathways associated with inflammatory skin disease such as psoriasis via TNF-α-dependent NF-κB activation." (PMID 29444128, 2018). "This study identifies the pathophysiological mechanism underlying anti-TNF-induced paradoxical psoriasis." (PMID 29295985, 2018). "Among a cohort of Danish patients with moderate-to-severe psoriasis, two SNPs in the IL12B and TNF genes were associated with susceptibility of psoriasis." (PMID 29389950, 2018). "Psoriasis is driven by T cell activation associated with the secretion of proinflammatory cytokines, including tumor necrosis factor-α (TNF-α), interleukin (IL)-17A, IL-22, and interferon IFN-γ." (PMID 30109481, 2018). "Despite that, no specific polymorphisms in the IL-17F gene have so far been associated with psoriasis susceptibility, although the IL-17F polymorphism rs763780 was linked to a better response to anti-TNF therapy." (PMID 30127781, 2018). "Future studies should evaluate the potential use of dual antagonism of IFN-γ and TNF-α in reducing vascular diseases associated with psoriasis." (PMID 29062018, 2017). "The pathogenesis of association of psoriasis with these disorders is attributed to a chronic inflammatory state, driven by activated T-cells and cytokines such as, tumor necrosis factor-α (TNF-α)." (PMID 28421157, 2017). "Compared to patients who received topical therapy, psoriasis patients treated with TNF-α inhibitors showed a significant decrease in the risk of myocardial infarction (hazard ratio 0.50)." (PMID 29065479, 2017). "Other studies have also confirmed the beneficial effects of TNF-α inhibitors in reducing the risk of myocardial infarction in psoriasis patients." (PMID 29065479, 2017). "A study found that TNF (SNP rs3093662) is a susceptible gene for psoriasis in the Chinese population." (PMID 29292715, 2017). "In this regard, a recent report showed that TNFAIP3 gene single nucleotide polymorphisms (SNPs) were associated with response to TNFα blockade in psoriasis." (PMID 28658319, 2017). "After this stimulation, the downstream effector molecules of Th17 cells, including IL-17A, IL-22, TNF-α, and IL-6 are produced in response to certain stimuli and subsequently induce keratinocyte proliferation and other hallmark features of psoriasis." (PMID 28900461, 2017). "TNF-α and IL-17 axis have been implicated in the pathogenesis of psoriasis and PsA, although there is a stronger IL-17 signature in the skin compared with the synovium." (PMID 29163483, 2017). "IL-8 and TNF-α are also involved in the course of psoriasis; high levels of TNF-α associated with NF-κB activation has been found in psoriatic patients." (PMID 28464025, 2017). "Of note, in patients with psoriasis, an absolute lymphocytosis associated to γδ T cell lymphoma after treatment with anti-TNF-α has been observed." (PMID 28222785, 2017). "Psoriasis has been associated with impaired Treg suppressive functions, resulting in overproduction of pro-inflammatory cytokines such as TNF-α and IFN-γ, as well as IL-17 and IL-22 produced by Th1 and Th17 effector cells, respectively." (PMID 29250057, 2017).
psoriasis (continued). "Data on TNF-inhibitors and the risk of TB, is mainly based on patients with rheumatic or inflammatory bowel disease which differ from psoriasis patients in the aspect of disease, co-morbidities, and concomitant treatments." (PMID 29104241, 2017). "Other proposed underlying mechanisms of secondary psoriasis include anti-TNF treatment-induced activation of autoreactive T-cells or certain infectious agents such as Streptococcus spp." (PMID 28905102, 2017). "In patients with psoriasis who were obese, weight loss has also been shown to increase the efficacy of anti-TNF-α biologic therapy." (PMID 29065479, 2017). "Elevated localized expression of TNFα has been shown to be one of the underlying causes for various autoimmune and inflammatory disorders such as psoriasis and arthritis." (PMID 28761167, 2017). "Clinical trials indicate that anti-TNF-α therapy in patients with psoriasis is associated with significantly decreased risk of myocardial infarction, compared to treatment with topical agents." (PMID 28460644, 2017). "We added psoriasis-associated cytokines of Th1 (TNFα, IL-6, and IL-1α) and Th17 (IL-17 and IL-22) origin to N/TERT1 HEEs during the last three days of the air-liquid interphase culture." (PMID 28928444, 2017). "Available evidence suggests that the risk of CD and UC during the course of psoriasis is more than twofold and nearly twice higher than in the general population, respectively, also after exclusion of patients treated with anti-TNF agents." (PMID 28905102, 2017). "Psoriasis was once thought to be a disease associated with the TNF-mediated Th1-type immune response." (PMID 29292715, 2017). "Psoriasis patients show elevated circulating levels of TNF-α compared with healthy subjects, and psoriasis has been associated with an increased incidence of ARDs." (PMID 26943583, 2016). "The hallmark of psoriasis is an extensive inflammation affecting the skin, mainly mediated by Th1/Th17 cytokines, with a key role of TNF-α." (PMID 27936119, 2016). "From that, probably the use of anti-TNF-α should be associated to an energy-restricted diet in order to improve psoriasis symptoms and lipid profile and to prevent the weight gain." (PMID 27377373, 2016). "According to current clinical studies, anti-TNF-α agents offer better evidence of benefit to lower the risk of cardiovascular diseases in patients with psoriasis." (PMID 27144162, 2016). "TNF-alpha polymorphism or TNF-alpha can increase the development of psoriasis or psoriatic arthritis." (PMID 26339139, 2015). "Effective treatment of psoriasis is associated with a decrease in IL-19 level and already within one week of treatment with Etanercept (targeting TNFα signalling) IL-19 expression was rapidly decreased." (PMID 25965695, 2015). "rs361525 (−238) in the TNFα gene has been associated with susceptibility to psoriasis, and the A allele was more frequent in male patients with type I psoriasis (p = 2E − 07)." (PMID 26613086, 2015). "We have recently shown that TNFR1 signaling in NF-κB-deficient epidermal keratinocytes drives psoriasis-like skin inflammation in mice, identifying keratinocytes as an important cellular target of pathogenic TNF signaling in skin inflammation." (PMID 25443631, 2014). "T cells have been implicated as key players in the maintenance of psoriasis and the pathogenesis appears to involve a cytokine network centered on IL-17/IL-23 and TNFα." (PMID 24665164, 2014). "Culture of dermal ECs with psoriatic cytokines (such as IFNγ, IL-17, and TNFα) also induced expression of many of the same chemokines found upregulated after transfection of ECs with psoriasis-associated CARD14 mutations." (PMID 25369198, 2014). "TNF -308 G/A polymorphism have been examined in several autoimmune and inflammatory diseases, such as psoriasis, lepromatous leprosy and systemic lupus erythematosus." (PMID 24498378, 2014).
psoriasis (continued). "Both TNFα and the IL-23/Th17 axis are strongly implicated in the pathogenesis of psoriasis, while IL-6 has recently been shown to be important in preventing immune suppression by regulatory T cells." (PMID 24665164, 2014). "A meta-analysis demonstrated TNF-α gene-308A/G polymorphism was associated with decreased risk of psoriasis." (PMID 25101759, 2014). "The clinical efficacy of anti-TNF-α drugs in patients with psoriasis and/or joint disease was associated with (i) reduction of IL-6 and IL-22 in sera; (ii) increments of regulatory T cells; (iii) reduction of cutaneous homing receptor expressing T cells." (PMID 25136144, 2014). "Electronic searches of Pubmed, Embase, and Web of Science were performed for all publications on the associations between TNF-α polymorphisms and psoriasis through September 26, 2012." (PMID 24324571, 2013). "A study performed in Caucasian patients with early-onset psoriasis showed a strong association with TNFα polymorphisms (rs1800629 and rs361525)." (PMID 24069534, 2013). "A study performed in an Egyptian population (46 cases and 96 controls) revealed an association between SNPs in TNFα (GG allele in rs1800629) and psoriasis (P < 0.05)." (PMID 24069534, 2013). "Subgroup analysis by ethnicity further identified a significant association between TNF-α 238 G/A polymorphism and increased risk of psoriasis in Caucasians." (PMID 24324571, 2013). "Psoriasis has been associated with genes involved in the immune response, namely, TNFα, IL12B, and IL23R." (PMID 24069534, 2013). "In current study, we provided a comprehensively assessment of the association between TNF-α 308 G/A polymorphism and psoriasis risk by performing a meta-analysis of 16 eligible studies." (PMID 24324571, 2013). "In this sense, a meta-analysis of 18 published case-control studies showed that when the GA + AA genotype was compared with the GG genotype, the risk of psoriasis increased for rs361525 and decreased for rs1800629 in TNFα gene." (PMID 24069534, 2013). "Subgroup analysis by ethnicity further showed that there was a significant association between TNF-α 308 G/A polymorphism and decreased risk of psoriasis in both Caucasians and Asians." (PMID 24324571, 2013). "TNF-α 308 G/A polymorphism was significantly associated with decreased risk of psoriasis under three genetic comparison models in Caucasian population." (PMID 24324571, 2013). "The meta-analysis suggests that TNF-α 308 G/A polymorphism is associated with decreased risk of psoriasis, while TNF-α 238 G/A is associated with increased risk of psoriasis." (PMID 24324571, 2013). "Overall, TNF-α 308 G/A polymorphism was significantly associated with decreased risk of psoriasis under three genetic comparison models when all 16 studies were pooled into the meta-analysis." (PMID 24324571, 2013). "In summary, this meta-analysis suggests TNF-α 308 G/A polymorphism is associated with decreased risk of psoriasis, while TNF-α 238 G/A is associated with increased risk of psoriasis." (PMID 24324571, 2013). "Second, on analyses the risk of psoriasis with TNFα promoter SNPs, patients only with PsV and/or PsA were involved, but not with erythroderma or pustular lesions." (PMID 23717605, 2013). "We performed a meta-analysis to evaluate the associations between TNF-α polymorphisms and psoriasis." (PMID 24324571, 2013). "TNF-α 308 G/A polymorphism was significantly associated with decreased risk of psoriasis under three genetic comparison models in Asian populations when those 3 studies were pooled into the meta-analysis." (PMID 24324571, 2013). "Although an association of polymorphisms in the TNF-α promoter region with psoriasis susceptibility has been reported in few previous studies, this problem remains still a matter for further research." (PMID 24324571, 2013). "But no studies investigated the gene-gene interactions in the associations of TNF-α 308 G/A and 238 G/A polymorphisms with psoriasis risk." (PMID 24324571, 2013).
psoriasis (continued). "In present study, we performed a meta-analysis to comprehensively evaluate the association between TNF-α 308 G/A polymorphism and psoriasis risk and the association between TNF-α 238 G/A polymorphism and psoriasis risk." (PMID 24324571, 2013). "We have previously shown that inflammatory DCs are important pathogenic cells in psoriasis, as they produce TNF, iNOS, IL-20, and IL-23, and are TRAIL+." (PMID 22348003, 2012). "Overexpression of tumor necrosis factor-α (TNFα) is believed to play a key role in the pathogenic mechanisms linking psoriasis and arthritis." (PMID 22649467, 2012). "Intriguingly, a recent epidemiological study found that among patients with RA or psoriasis, the adjusted risk of new-onset DM was lower for individuals on TNF inhibitor (adjusted hazard ratio 0.62) compared with initiation of other non-biologic DMARDs." (PMID 22691241, 2012). "Since increased TNF-α is known to be associated with many pathological conditions, such as infection/inflammation, psoriasis, as well as cancers, the inhibitory effect of ACW on TNF-α potentially has a wild-range of applications." (PMID 22754342, 2012). "Homozygous carriers of the TNF-238A allele were more frequent among patients with psoriasis compared to controls." (PMID 21408088, 2011). "In psoriasis, the pathogenic role of TNF-α has been demonstrated by the effective treatment of patients with anti-TNF therapies." (PMID 21483750, 2011). "Pustular psoriasis and psoriasis are an uncommon but recognized adverse event associated with TNF-α inhibition." (PMID 18727822, 2008). "Agents central to psoriasis or PsA management—such as TNF inhibitors and IL-17 inhibitors—may be associated with photosensitive rashes, de novo CLE, drug-induced lupus, or SLE exacerbations in susceptible individuals." (PMID 41596733, 2026). "It is recognized that some cytokines, particularly TNF-α and IL-6 which are frequently seen in psoriasis and OSA could induce sleep and may cause EDS." (PMID 40232659, 2025). "The bidirectional association between OSA and psoriasis suggests a common systemic inflammatory pathway The activity of IL-7, TNF, IL-6, and C-reactive protein was significantly increased in OSA patients, and the increase of this activity was also significantly correlated with psoriasis." (PMID 40166062, 2025). "Therapeutic agents targeting inflammatory pathways, such as TNF-α inhibitors, IL- 12/IL- 23 inhibitors (ustekinumab), and IL- 17/IL- 23 inhibitors, improve psoriasis management and may mitigate CVD risk." (PMID 40229608, 2025). "Compared with monoculture, psoriasis-derived mesenchymal stromal cells (PsO-MSCs) co-cultured with healthy donor MSCs (H-MSCs) secreted substantially lower levels of hallmark psoriatic pro-inflammatory cytokines (IL-6, IL-12, IL-13, IL-17A, TNF, and G-CSF)." (PMID 41226338, 2025). "More severe forms of psoriasis are associated with a high degree of inflammation, that are confirmed by psoriatic skin lesions and numerous inflammatory mediators such as TNFα, IL-1, IL- 6, IL-8, IL-17, IL-22, IL-23, INF-ɣ, homocysteine and hsCRP, which highly correspond with disease activity." (PMID 39858442, 2025). "Additionally, several pro‐inflammatory cytokines such as TNF‐α, IL‐6, IL‐23 and IL‐17 are implicated in the onset and pathogenesis of both psoriasis and periapical lesions." (PMID 40105908, 2025). "TNF-α had a pivotal role in psoriasis disease progression The higher level of TNF-α could be associated with worse disease than the patient with a lower TNF-α level." (PMID 38712377, 2025). "Potential pathogenic mechanisms linking psoriasis with metabolic syndrome include releasing large amounts of proinflammatory cytokines such as interleukins (IL-17, IL-23) and tumor necrosis factor alpha (TNF-α)." (PMID 40559401, 2025).
psoriasis (continued). "In this study, in order to explore the relationship between PGGT1B deficiency and inflammation in psoriasis, we also detected the mRNA and cytokine expressions of inflammatory factors IL-1β, IL-6, TNF-α, IL-17A, and IL-10 in the most serious stage of skin injury in mice." (PMID 40430037, 2025). "Psoriasis was initially associated with Th1 cells and their cytokines, including TNF-α and IFN-γ." (PMID 40906403, 2025). "Similar to ACD, psoriasis is caused primarily by TNF-α, IL-1β, and IL-6 produced by keratinocytes, which stimulate plasmacytoid dendritic cells to produce interferon-α (IFN-α) followed by its stimulation of IL-12 and IL-23 release by dendritic cells nearby lymph nodes." (PMID 41226679, 2025). "In psoriasis, skin lesions arise from complex processes involving maladaptive immune signalling among keratinocytes, dendritic cells, neutrophils and T-cells; implicated pathways include IL-17A, IL-22, IL-23 and TNF-α signalling." (PMID 39959848, 2025). "Both IFN-γ and TNF-α are known to induce the expression of IL-6, IL-8, IL-12, and IL-18, thereby constituting a key regulatory axis within the cytokine network implicated in psoriasis." (PMID 40731810, 2025). "Genetic variations and psoriasis susceptibility: studies have identified several genetic loci associated with psoriasis, particularly in genes related to immune responses, such as IL-23 and TNF-α pathways." (PMID 39860587, 2025). "Increased IFNα release can cause psoriasis, while TNF blockade might decrease Th1 and Th17 cell accumulation at inflammation sites, causing compensatory expansion elsewhere." (PMID 40565205, 2025). "However, some studies have shown that TNF-α inhibitors are associated with an increase in body weight and body mass index in patients with psoriasis." (PMID 40584532, 2025). "In order to explore the relationship between PGGT1B deficiency and inflammation in psoriasis, we measured the mRNA and cytokine expressions of inflammatory factors IL-1β, IL-6, TNF-α, IL-17A, and IL-10 in the most serious stage of skin injury in mice using Luminex and qRT-PCR." (PMID 40430037, 2025). "Clinically, the observation that biologics targeting IL-17 or TNF not only improve psoriasis but may also lower AD risk provides further support for the relevance of these shared mechanisms." (PMID 41465136, 2025). "The observed association between APS autoantibody positivity and TNF inhibitor treatment or clinical parameters suggests a potential immunomodulatory interplay between autoimmunity and inflammation in the pathogenesis of psoriasis." (PMID 38987260, 2024). "Interestingly, we found the minor allele of TNF-α-308 (rs1800629) to be associated with a poor response to TNFi when assessing all CIDs together, but only for psoriasis when the diseases were examined individually." (PMID 38891983, 2024). "Endothelial and platelet MV levels are decreased in psoriasis patients treated with anti-TNF-α medications, which may reduce the risk of cardiovascular complications." (PMID 38927529, 2024). "Moreover, TNF-α, as a homotrimer cytokine, is associated with cell cycle alteration particularly in keratinocytes and hair follicles in psoriasis." (PMID 39057098, 2024). "Similarly, pathogenic TRM cells were detected in patients with psoriasis even 6 years after TNF inhibitor treatment." (PMID 39682698, 2024). "However, more recent studies on anti-TNFα therapies appear to exclude a link with increased risk of cancer in RA, psoriasis, and IBD." (PMID 39359726, 2024). "Notably, the TNF-α gene −238G>A polymorphism (rs361525) has been related to increased incidence of psoriasis." (PMID 39063004, 2024). "This suggests that TNF-α, a core pathogenic factor in psoriasis, may disrupt the skin barrier by downregulating LOR genes." (PMID 38606161, 2024). "However, ADA but not guselkumab decreased serum CCL4/MIP-1β levels, a marker associated with psoriasis and downstream of TNF-α." (PMID 39114670, 2024).